COL11A1 (collagen type XI alpha 1 chain)
Description:
May play an important role in fibrillogenesis by controlling lateral growth of collagen II fibrils.
Synonyms: COLL6; STL2; CO11A1; DFNA37
Tractability: Antibody: its Gene Ontology location is reachable by antibodies, with high confidence; UniProt places it where antibodies can reach, with medium confidence; UniProt predicts a signal peptide or a membrane-spanning region. PROTAC: ubiquitination databases record sites on it. Other modalities: an approved drug acts on it.
Gene: Protein-coding gene on chromosome 1 (102,876,467 to 103,108,872, reverse strand). Ensembl gene ENSG00000060718.
Subcellular location: Secreted, extracellular space, extracellular matrix
Subcellular location (Human Protein Atlas): Endoplasmic reticulum; Predicted to be secreted
Pathways (Reactome):
Extracellular matrix organization: Assembly of collagen fibrils and other multimeric structures; Collagen biosynthesis and modifying enzymes; Collagen chain trimerization; Collagen degradation; Non-integrin membrane-ECM interactions
Developmental Biology: Developmental Lineage of Pancreatic Ductal Cells
Signal Transduction: MET activates PTK2 signaling
Gene Ontology:
Molecular function: extracellular matrix binding; extracellular matrix structural constituent; extracellular matrix structural constituent conferring tensile strength; protein-macromolecule adaptor activity
Biological process: detection of mechanical stimulus involved in sensory perception of sound; endodermal cell differentiation; sensory perception of sound; visual perception; collagen fibril organization; skeletal system morphogenesis
Cellular component: collagen type XI trimer; endoplasmic reticulum; extracellular matrix; endoplasmic reticulum lumen; extracellular region; collagen trimer
Genetic constraint (gnomAD): Loss-of-function variants: 51 observed, 184.45 expected, observed/expected ratio (o/e) 0.28, 90% interval 0.22 to 0.35. The upper end of that interval is the gene's LOEUF score, 0.35, which puts it in group 1 of 6, group 1 being the genes least tolerant of losing a copy. Missense variants: 1,807 observed, 1,929 expected, observed/expected ratio (o/e) 0.94, 90% interval 0.9 to 0.97. Synonymous variants: 679 observed, 631.93 expected, observed/expected ratio (o/e) 1.07, 90% interval 1.01 to 1.14.
Gene-disease validity (ClinGen):
ClinGen rates the evidence that COL11A1 causes each of these diseases.
autosomal dominant nonsyndromic hearing loss (autosomal dominant): Moderate. Autosomal dominant form of nonsyndromic deafness.
Homologues: Orthologues: macaque COL11A1 (99% identical), chimpanzee COL11A1 (98% identical), rabbit COL11A1 (97% identical), pig COL11A1 (96% identical), dog COL11A1 (95% identical), rat Col11a1 (94% identical), mouse Col11a1 (94% identical), guinea pig COL11A1 (91% identical), tropical clawed frog col5a3 (82% identical), zebrafish col11a1a (80% identical), zebrafish col11a1b (75% identical). Paralogues in human: COL5A1 (75% identical), COL11A2 (65% identical), COL5A3 (57% identical), COL2A1 (37% identical), COL1A1 (36% identical), COL27A1 (36% identical), COL24A1 (35% identical), COL5A2 (34% identical), COL3A1 (34% identical), COL4A5 (33% identical), COL4A1 (32% identical), COL1A2 (32% identical), and 25 more.
Diseases named in the same sentence as COL11A1 in open-access papers:
COL11A1 is named in the same sentence as 229 diseases in open-access papers, as found by Europe PMC text mining. Sharing a sentence is not in itself a finding about the gene and the disease. The quoted sentences say what the papers report.
Stickler syndrome (70 papers, 2008 to 2026). Stickler syndrome is an inherited vitreoretinopathy characterized by the association of ocular signs with more or less complete forms of Pierre-Robin sequence, bone disorders, and sensorineural deafness (10% of cases). "COL2A1 and COL11A1 were responsible for Stickler syndrome (15%, 6/40) and VCAN was associated with Wagner syndrome (5.0%, 2/40)." (PMID 40270540, 2025). "Genetic testing via whole-exome sequencing identified a COL11A1 (collagen type XI alpha 1 chain) gene variant (c.4032G>A, p.Pro1344=; NM_001854.4), associated with Stickler syndrome type 2 (STL2), an autosomal dominant heterozygous disorder." (PMID 40144770, 2025). "Other conditions, such as COL11A1 (included in four of five panels) can be associated with cataracts and Stickler syndrome with an increased risk of retinal detachment." (PMID 36981008, 2023). "It is important to note that chondrodystrophies linked to COL11A1 present as a spectrum of disorders varying in severity, such as Stickler’s syndrome." (PMID 36278545, 2022). "As with exon 2 in type 1 Stickler syndrome so the natural alternative splicing of COL11A1 exon 9 modifies the effect of such mutations reducing the severity of the associated skeletal dysplasia." (PMID 34611315, 2022). "Genetic mutations of COL2A1 and COL11A1 seen in Stickler Syndrome affect the incidence of mandibular distraction osteogenesis." (PMID 35198553, 2022). "Pathogenic variants in COL11A1 are known to cause both the Marshall and Stickler type 2 syndromes, rare autosomal dominant disorders along with other ocular, orofacial, auditory, and skeletal manifestations." (PMID 35736209, 2022). "Note that COL11A2 heterotrimer partner COL11A1 is associated with both eBMD and OA traits and causes Stickler syndrome with fragility fractures." (PMID 35057801, 2022). "Mutations in COL11A1 cause Stickler syndrome, Marshall syndrome, and Stickler-like syndrome which are manifested by abnormal collagen in the sclera with axial myopia." (PMID 36036827, 2022). "Type 2 Stickler syndrome is caused by pathogenic variants of the COL11A1 gene, which codes for the α1 chain of type XI collagen." (PMID 35741851, 2022). "Most heterozygous COL11A1 mutations linked to Stickler syndrome are supposed to result in a dominant-negative effect." (PMID 36140739, 2022). "The COL11A1 gene mutations in type XI collagen are associated with Stickler syndrome, Marshall syndrome, fibrochondrogenesis." (PMID 34572492, 2021). "Hearing loss is thought to be more common and more severe in type 2 Stickler Syndrome, caused by mutations in COL11A1, than in type 1 Stickler syndrome." (PMID 32901364, 2021). "Human mutations in COL11A1 result in similar abnormalities that constitute the Marshall and Stickler syndromes." (PMID 32872105, 2020). "With regard to Stickler syndrome, we identified pathogenic variants in the COL11A1 (two cases) and COL11A2 (one case) genes." (PMID 31427586, 2019). "Mutations in the COL11A1 gene have been found in patients with Marshall syndrome and Stickler syndrome, which share similar phenotypes, such as craniofacial abnormalities, a flat nasal bridge, midface hypoplasia, a short nose, palate defects and hearing loss." (PMID 27188386, 2017). "Marshall syndrome [MIM:154780], which is caused by mutations in COL11A1, has a clinical overlap with Stickler syndrome." (PMID 28841907, 2017). "Mutations in COL11A1 cause Marshall syndrome, Stickler syndrome, and Stickler-like syndrome; these disorders are all characterized by midfacial hypoplasia, sensorineural hearing deficit, and nonprogressive axial myopia." (PMID 24282630, 2013). "The differential included fibrochondrogenesis type 1 (OMIM #228520) caused by COL11A1 as well as Stickler syndrome (OMIM #108300) hence multiple genes could be potentially causative; thus, WES was an appropriate strategy." (PMID 34092239, 2021).
Stickler syndrome (continued). "Although their cancer incidence is unreported, the very rare autosomal dominant connective tissue disorders, Stickler and Marshall syndromes, can be caused by similar mutant COL11A1 glycine substitutions in the Gly-X-Y tripeptide, indicating that such mutations can act dominantly." (PMID 34584216, 2021). "In the majority of type 2 Stickler Syndrome cases, the pathogenic variant is a missense change or an in-frame deletion and the abnormal COL11A1 pro-alpha chain exerts a dominant negative effect on normal type XI collagen expression in the cochlear extracellular matrix." (PMID 32901364, 2021). "Previously, COL11A1 was solely associated with Marshall and Stickler syndromes." (PMID 30245514, 2019). "Interestingly, all three collagen genes (Col2a1, Col9a1, Col11a1) related to extracellular matrix degradation and enriched in expression in the peripheral retina are known to cause the Stickler Syndrome." (PMID 31108889, 2019). "Mutations in the type XI collagen genes col11a1 and col11a2 have previously been linked to numerous skeletal dysplasias, such as Stickler syndrome and fibrochondrogenesis, which are associated with cartilage destabilization, and abnormal skeletal shape and properties." (PMID 30249781, 2018). "Marshall syndrome, caused by a COL11A1 mutation, has clinical overlap with Stickler syndrome." (PMID 28841907, 2017). "Defects in COL11A1 are known to cause Stickler and Marshall syndromes." (PMID 29053642, 2017). "Mutations in COL11A1 cause disorders characterized by midfacial hypoplasia, sensorineural-hearing deficit, and nonprogressive axial myopia, such as Marshall syndrome, Stickler syndrome, and Stickler-like syndrome." (PMID 27824919, 2016). "Interestingly, COL11A1 mutations are also known to cause Marshall syndrome or Marshall/Stickler syndrome, which both have myopia as a common feature." (PMID 21527992, 2011). "In addition to cataracts, both Marshall and Stickler syndrome can include myopia and sensorineural hearing loss, phenotypes which are also present in the proband’s father (II.1); the COL11A1 variant could explain the deafness in the proband." (PMID 40301690, 2025). "Stickler Syndrome, primarily caused by variants in COL2A1 and COL11A1, represents the most common form, accounting for approximately 80%–90% of cases." (PMID 40270540, 2025). "Biallelic pathogenic mutations in COL9A1 have also been associated with Stickler syndrome with ocular abnormalities, alongside more common causes of Stickler syndrome caused by mutations in COL2A1 and COL11A1." (PMID 41153400, 2025). "By contrast, Stickler syndrome has the most collagens (six) linked to this syndrome (COL2A1, COL9A1, COL9A2, COL9A3, COL11A1, and COL11A2), followed by Ullrich congenital muscular dystrophy, with four collagens associated (COL6A1, COL6A2, COL6A3, and COL12A1)." (PMID 37189830, 2023). "DNA analysis identified a single nucleotide substitution (c.1874G > T) in exon 19 of COL11A1, predicted to result in an amino acid substitution of a triple helix glycine (p.Gly625Val) in the α1 chain of type XI procollagen (type 2 Stickler syndrome)." (PMID 34611315, 2022). "A membranous type of congenital vitreous anomaly is mainly seen in type 1 Stickler syndrome (STL1, COL2A1), whereas a beaded vitreous anomaly is often associated with type 2 Stickler syndrome (STL2, COL11A1)." (PMID 36140739, 2022). "Pathogenic variants in COL11A1 have been associated with nonsyndromic forms of HL DFNA37 [MIM: 618533], and syndromic HL associated with Marshall and Stickler Syndromes [MIM: 154780 and 604841]." (PMID 34837038, 2022). "COL11A1- and COL11A2-related Stickler syndrome results in more frequent hearing loss, being moderate and involving all frequencies." (PMID 36140739, 2022). "In this study, we report genetic analysis of 37 Korean patients with Stickler syndrome, which revealed 21 variants including 11 novel variants in COL2A1 and COL11A1." (PMID 34680973, 2021).
Stickler syndrome (continued). "This multi-center study was able to broaden the genetic variation spectrum of COL2A1 and COL11A1 genes in Korean patients with Stickler syndrome." (PMID 34680973, 2021). "The known causative genes of Stickler syndrome are COL2A1, COL11A1, COL11A2, COL9A1, COL9A2, and COL9A3." (PMID 34680973, 2021). "The corresponding phenotypic disorders of the mutated POU4F3, COL11A1, OCA2 are autosomal dominant deafness type 15, Marshall syndrome (or Stickler syndrome) and eye pigment variant I, respectively." (PMID 33345266, 2021). "Stickler syndrome caused by COL2A1, COL11A1, and COL11A2 genes has a dominant inheritance, whereas COL9A1, COL9A2, and COL9A3 genes show a recessive inheritance." (PMID 34680973, 2021). "To date, mutations in seven genes (COL2A1, COL11A1, COL11A2, COL9A1, COL9A2, COL9A3, and LOXL3) have been reported to cause Stickler syndrome." (PMID 32756486, 2020). "Stickler syndrome type 2 [MIM:604841] is the second most common, caused by mutations in the COL11A1 gene [MIM:120280] on chromosome 1p21." (PMID 28841907, 2017). "To date, multiple mutations in the collagen-encoding genes COL2A1, COL11A1, COL11A2, COL9A1, COL9A2, and COL9A3 have been associated with six genetically distinct types of Stickler syndrome." (PMID 28335520, 2017). "In humans, Stickler syndrome caused by mutations of COL2A1, COL11A1, COL11A2, COL9A1 and COL9A2, is one of the most common connective tissue disorders characterized by ocular, skeletal, orofacial and auditory defects." (PMID 26307084, 2015). "Stickler syndrome is commonly caused by mutations in different collagen genes, namely COL2A1, COL11A1 and COL11A2 (autosomal dominant inheritance) and COL9A1 and COL9A2 (autosomal recessive inheritance)." (PMID 26307084, 2015). "Here we have described the design and utilization of MLPA probes sets that cover 57 of the 68 exons of the COL11A1 gene, and have detected six novel deletions in patients with Stickler syndrome that would have been overlooked by exon sequencing alone." (PMID 23621912, 2013). "Variants of Stickler syndrome have been designated STL1 (vitreous type with mutations in COL2A1 gene), STL2 (early onset hearing loss and mutations in the COL 11A1 gene) and STL3 (non-ocular type caused by mutations in the COL11A2 gene)." (PMID 18950500, 2008). "A recent meta-analysis of 400 eyes of 225 patients with COL2A1- or COL11A1-related Stickler syndrome reported an RD rate of 6.6% (6.3 years mean follow-up duration) in patients who had prophylactic laser retinopexy compared to 36.0% (4.0 years mean follow-up duration) in patients without laser." (PMID 41153400, 2025). "Several of these genes are implicated in systemic disorders that can feature retinal involvement, including KIF11 (microcephaly–lymphedema–chorioretinal dysplasia), COL11A1 (Stickler syndrome), PHYH (Refsum disease), and TUBB4B (Leber congenital amaurosis with early-onset deafness)." (PMID 40923693, 2025). "RRD is related to pathological mechanical changes in the vitreoretinal interface (e.g., posterior vitreous detachment, PVD; lattice degeneration, 30–46% of RRD); thus, genetic variants in collagen genes (e.g., COL2A1, COL11A1, COL18A1) are logically implicated in Stickler syndrome." (PMID 41465105, 2025). "For example, a heterozygous pathogenic variant in the alternatively spliced exon 9 of COL11A1 in trans with another COL11A1 pathogenic variant results in Stickler syndrome and not in the often lethal fibrochondrogenesis." (PMID 40158061, 2025). "Exome sequencing identified 21 potential pathogenic variants of 13 genes in 20 of 75 (26.7%) probands, including genes for Stickler syndrome (COL11A1 and COL2A1; 6/20), FEVR (FZD4, LRP5, and TSPAN12; 5/20), and others (FBN1, GPR179, ZEB2, PAX6, GPR143, OPN1LW, FRMD7, and CACNA1F; 9/20)." (PMID 38243264, 2024). "Some years later, disease-causing mutations in the COL11A1 and COL11A2 gene could also be associated with a Stickler syndrome phenotype." (PMID 36140739, 2022).
Stickler syndrome (continued). "This case demonstrates that effects of some recessive mutations in COL11A1 can be modified by alternative splicing and result in type 2 Stickler syndrome rather than fibrochondrogenesis." (PMID 34611315, 2022). "However, COL11A1‐related disease accounts for only 10–20% of Stickler syndrome worldwide while COL2A1‐related disease accounts for 80–90% of cases." (PMID 33951325, 2021). "COL11A1‐related disease accounts for 10%–20% of Stickler syndrome." (PMID 33951325, 2021). "Lastly, for individual U071, the diagnosis was Stickler syndrome/Marshall syndrome (COL11A1)." (PMID 32963807, 2020). "In addition to skeletal symptoms, chondrodystrophies such as Stickler syndrome also includes hearing loss, and the zebrafish model system may provide insight into the mechanism that links the skeletal phenomena to hearing loss, resulting from mutations in the Col11a1 gene." (PMID 32872105, 2020). "Mutations in the COL2A1, COL11A1, and COL11A2 procollagen genes cause Stickler syndrome." (PMID 28841907, 2017). "It is estimated that 80%–90% of all Stickler syndrome cases are associated with pathological variants in COL2A1 (Type I), 10%–20% of cases are COL11A1-related (Type II), and Types III-VI are rare and of an unknown prevalence." (PMID 28335520, 2017). "Indeed, mutations in COL2A1, COL11A1, COL11A2, COL9A1, COL9A2, and COL9A3 have been associated with Stickler syndrome and early-onset OA." (PMID 28335520, 2017). "Type II Stickler syndrome (COL11A1) is the second most common type of Stickler syndrome." (PMID 23110709, 2012). "Similarly, mutations in the collagen-α chain genes, COL2A1, COL9A2, COL11A1, and COL11A2, have been associated with different forms of Stickler syndrome (OMIM#108300, #614284, #604841, and #184840, respectively), a clinically variable condition that includes cleft palate." (PMID 28106045, 2017). "The other detected genes in this study, such as those related to Stickler syndrome (COL2A1 and COL11A1) or Marfan syndrome (FBN1), which have been proposed to modulate ocular growth through axial mechanism." (PMID 38243264, 2024). "These genes are associated with recognizable syndromes such as (acampomelic) campomelic dysplasia (SOX9), cerebro‐costo‐mandibular syndrome (SNRPB), SATB2‐associated syndrome (Glass syndrome, SATB2), Catel‐Manzke syndrome (TGDS), TARP syndrome (RBM10), and Stickler syndrome (COL2A1, COL11A1)." (PMID 41077824, 2026). "Notably, the most common pathogenic genes in high myopia cases with retinal detachment were those related to Stickler syndrome, particularly COL2A1 (10.0%, 4/40) and COL11A1 (5.0%, 2/40)." (PMID 40270540, 2025). "Consistent with previous studies, retinal detachment developed in 58.2% of patients with COL2A1-related Stickler syndrome who did not undergo laser prophylaxis, compared to 37.5% of patients with COL11A1-related Stickler syndrome." (PMID 41153400, 2025). "These systemic syndromes can be caused by a series of genes, including NYX, CACNA1F, GRM6, and LRIT3, responsible for congenital stationary night blindness (CSNB); COL2A1, COL11A1, COL9A1, and COL9A2, responsible for Stickler syndrome; and FBN1, responsible for Marfan syndrome." (PMID 36980859, 2023). "In COL9A1-related autosomal recessive Stickler syndrome, the vitreous does not phenocopy the classic type 1 Stickler syndrome (COL2A1; membranous vitreous) or type 2 Stickler syndrome (COL11A1; beaded vitreous) patterns." (PMID 41153400, 2025).